MMP3 (matrix metallopeptidase 3)
Diseases named in the same sentence as MMP3 in open-access papers (continued):
Sharing a sentence is not in itself a finding about the gene and the disease.
COVID-19 (19 papers, 2021 to 2026). A disease caused by infection with severe acute respiratory syndrome coronavirus 2. "Similar to MMP-2, MMP-3 is implicated in the onset of neurological damage in COVID-19 and is upregulated by the spike protein of SARS-CoV-2." (PMID 37372128, 2023). "A strength of this study is represented by new findings of an association of MMP3 versus COVID-19 severity and MMP9 versus inflammation." (PMID 35075175, 2022). "Further studies focusing on susceptibility and prognosis and MMP-3 variants hold great potential for risk stratification and treatment of many viral conditions, COVID-19 being the most renowned to date." (PMID 35204780, 2022). "Our results also indicate a possible role for MMP-1 and MMP-3 in lung injury associated with COVID-19, two matrix metalloproteases implicated in tissue damage underlying other lung diseases." (PMID 33995342, 2021). "Therefore, an increase in MMP-3 serum levels on hospital admission was reported, characterizing the presence of an inflammatory state caused by COVID-19, with a subsequent reduction in MMP-3 levels after 1 month of cessation of systemic inflammation." (PMID 37372128, 2023). "The matrix metalloproteinases MMP-1 and MMP-3 are implicated in tissue damage underlying other lung diseases (D'Armiento and others 1992; Dahlen and others 1999; Greenlee and others 2007), placing them as potential therapeutic objectives to reduce lung injury in COVID-19." (PMID 35674675, 2022). "For instance, in a recent work, MMP-3 was shown to be significantly elevated in COVID-19 patients compared to healthy controls, indicating its potential role in diagnosing the disease." (PMID 40943488, 2025). "In the same way, a correlation between MMP-3 serum levels and the severity of COVID-19 pulmonary symptoms has been also assessed." (PMID 36674321, 2023). "Recently, Shi and others (2020b) found higher serum concentrations of MMP-3 in COVID-19 patients than in healthy individuals, and their levels correlated with inflammatory markers such as IL-6 and IL-1β." (PMID 35647937, 2022). "Nonetheless, validation studies are required to demonstrate a link between TWEAK, TLSP, MMP-1, and MMP-3 and severe COVID-19." (PMID 35674675, 2022). "In clinical studies, plasma levels of MMP-2, MMP-3, and MMP-9 were associated with the severity of patients with COVID-19." (PMID 36142454, 2022). "Serum levels of MMP3 were significantly higher in COVID-19 patients as compared with a control group of healthy subjects, and gradually increased with the WHO stage." (PMID 35075175, 2022). "For these reasons, the pharmacological inhibition of MMP3 was suggested as a potential therapeutic option in COVID-19 patients with severe ARDS8." (PMID 35075175, 2022). "Similarly, it has been reported that serum MMP-3 levels increased progressively with the severity of COVID-19, while MMP-9 levels were significantly higher in patients with severe forms of the disease, although they did not correlate directly with severity." (PMID 40943488, 2025). "Furthermore, serum MMP-3 levels were related to the severity of lung injury in patients with COVID-19." (PMID 37372128, 2023). "Another MMP that was elevated in the serum of COVID-19 patients is MMP-3 (stromelysin-1)." (PMID 35563537, 2022). "Conversely, TWEAK, TSLP, MMP-1, and MMP-3 are upregulated only in COVID-19." (PMID 35674675, 2022). "Furthermore, it was found that serum levels of MMP-3 were related to the severity of pulmonary expression of COVID-19 patients." (PMID 35075175, 2022). "Similarly, acute COVID-19 is also characterized by elevated levels of MMP-3, 7 and 9 in comparison to convalescent COVID-19 and other diseases controls." (PMID 36544496, 2022). "Circulating MMP-9 was further measured in COVID-19 patients in addition to the MMP-3 to see if they could predict the severity of the disease as assessed by the World Health Organization (WHO) severity stage." (PMID 36482481, 2022). "TWEAK, TSLP, MMP-1, and MMP-3 were elevated in COVID-19 cases." (PMID 33995342, 2021).
COVID-19 (continued). "In this study, matrix metalloproteinase MMP-3 and microenvironment remodeling factors including MCP-3, MIF, IL-8, SDF-1, and SCYB16 were detected as highly expressed cytokines in COVID-19." (PMID 38476443, 2024). "Metalloproteases have a longstanding link to the progression of respiratory damage, and MMP-2, MMP-3, MMP-7, and MMP-9 have all been shown to correlate with COVID-19 severity." (PMID 36298651, 2022). "Interestingly, the distribution of MMP3 serum levels in COVID-19 patients are highly variable, thus we suggest that preliminary analysis of serum MMP3 at hospital admission may help to predict the severity of lung damage and to select COVID-19 patients that may benefit from targeted therapies." (PMID 35075175, 2022). "To better define the role of MMP3 and MMP9 as biomarkers of COVID-19 outcome, we studied serum levels of these proteins in 108 patients with COVID-19 and in 48 healthy subjects." (PMID 35075175, 2022). "We studied serum MMP3 and MMP9 as potential biomarkers of COVID-19 severity, in 108 hospitalized patients with different World Health Organization (WHO) severity stage and in 48 controls." (PMID 35075175, 2022). "Alongside the significant elevation of MMP-1 observed in COVID-19 patients, there have been reports indicating that the SARS-CoV-2 spike protein can stimulate the expression of MMP-2 to a lesser extent, as well as MMP-3." (PMID 37372128, 2023). "Although serum levels of MMP-3 increased after one week of hospitalization, expression levels of MMP-9 did not change with advancing disease stages, despite being higher in those affected by COVID-19." (PMID 37372128, 2023). "These therapies would have a role, considering that we demonstrated that steroids (commonly used in COVID-19 patients that require oxygen supplementation) do not modulate serum levels of MMP3." (PMID 35075175, 2022). "The increase of serum/plasma levels of MMP3 and MMP9 during COVID-19 was already reported." (PMID 35075175, 2022). "In conclusion, serum MMP3 may help to early predict the severity of COVID-19 and both proteins, MMP3 and MMP9, may contribute to define severe COVID-19 patients that may benefit from a targeted therapy on MMPs." (PMID 35075175, 2022). "MMP-3, which regulates the ECM, was also differentially upregulated in the post-COVID-19 airway." (PMID 35151371, 2022). "Meanwhile, COVID-19 displayed an immune profile distinguished by increased Th1 (IL-12, IFN-γ) and Th2 (IL-4, IL-5, IL-10, IL-13) cytokine levels, along with IL-1β, IL-6, CCL11, VEGF, TWEAK, TSLP, MMP-1, and MMP-3." (PMID 33995342, 2021).
cervical carcinoma (18 papers, 2007 to 2025). A carcinoma arising from either the exocervical squamous epithelium or the endocervical glandular epithelium. "BCYRN1 knockdown in cervical cancer has also been shown to disrupt tumor growth, reduce MMP3 and VEGF expression, and enhance miR-138 expression." (PMID 35730016, 2022). "The 5-year survival of MMP3-high cervical cancer patients was 51%, while that of the MMP3-low expression group was 71%." (PMID 32260433, 2020). "Recently one study found several novel genes to be differentially expressed in cervical cancer and was overexpressed in cervical cancers, confirmed by immunohistochemistry such as MMP3, UBE2C and p16 protein." (PMID 23505442, 2013). "In addition, MMP-3, -10 and -13 were expressed in cervical carcinoma and teratocarcinoma cell lines only." (PMID 20942921, 2010). "MMP3 has been reported to be expressed in lymph node metastasis and in recurrent cervical cancers." (PMID 19832977, 2009). "This study constructed a cervical cancer prognosis model based on MPT‐driven necrosis‐related genes (ICOS, MMP3, POSTN) by integrating single‐cell and transcriptomic data." (PMID 40747615, 2025). "Functional validation further indicated that the silencing of MMP3 and POSTN significantly impedes the proliferation and migration of cervical cancer cells." (PMID 40747615, 2025). "MMP3, UBE2C and p16 protein overexpression in cervical cancers was confirmed by immunohistochemistry." (PMID 21338529, 2011). "Immunohistochemistry was used to study the protein expression of MMP3, UBE2C and p16 in normal, dysplasia and cancers of the cervix." (PMID 21338529, 2011). "IL‐6 was used to activate STAT3 signaling pathway in HeLa and SiHa cells, and the expression of N‐cadherin, E‐cadherin, vimentin, MMP‐3, and MMP‐13 were examined to confirm the activation of the STAT3 signaling pathway to promote the invasion potential of cervical cancer cells." (PMID 33040485, 2020). "HeLa and SiHa cells were treated with RES and S3I201 or AG490, and the expression levels of N‐cadherin, E‐cadherin, vimentin, MMP‐3, and MMP‐13 were examined to confirm that the role of STAT3 phosphorylation was inhibited by RES on the invasion potential of cervical cancer cells." (PMID 33040485, 2020). "The protein levels of p‐STAT3 (Tyr705), N‐cadherin, E‐cadherin, vimentin, MMP‐13, and MMP‐3 in the tumor tissues grown from HeLa cells were determined through IHC and Western blot to examine the effects of RES on STAT3 phosphorylation, EMT, and cervical cancer cell invasion." (PMID 33040485, 2020).
Alzheimer disease (17 papers, 2014 to 2025). A progressive, neurodegenerative disease characterized by loss of function and death of nerve cells in several areas of the brain leading to loss of cognitive function such as memory and language. "Other studies reported the associations of the MMP3 -1171 6A allele with the risk of Alzheimer’s disease and its earlier onset." (PMID 39769228, 2024). "In a Slovakian cohort study, MMP2 rs243865 and MMP3 rs3025058 promoter polymorphisms were shown to impact on the onset of Alzheimer’s disease." (PMID 36232390, 2022). "Elevated brain levels of MMP3 have been associated with the duration of Alzheimer's disease, and it has been found to increase the activity of MMP9, thereby indirectly promoting aggregation and cerebral accumulation of tau deposits." (PMID 33869630, 2021). "Increased expression of MMP-3 is also observed in the cerebrospinal fluid of patients with Alzheimer’s disease, and levels of MMP-3 are associated with the duration of the disease." (PMID 33182618, 2020). "Particularly important, MMP-3 activity has been implicated in the pathophysiology of Parkinson’s disease, Alzheimer’s disease, and ischemic neuronal death." (PMID 27351676, 2017). "Variants in associated with ACE and those associated with MMP3 levels also show association with risk for Alzheimer's disease in the expected directions." (PMID 25340798, 2014). "MMP3, also known as stromelysin-1, has been associated with pathogenesis of neurodegenerative disease including Alzheimer's disease (AD) and Parkinson's disease (PD)." (PMID 24416274, 2014). "MMP-3 levels correlate to the duration of Alzheimer’s disease and with CSF T-tau and P-tau levels in the elderly controls." (PMID 36232390, 2022). "MMP-10 is increased in CSF of patients with Alzheimer’s disease and MMP-3 is elevated in mixed dementia (unpublished data)." (PMID 30533010, 2018). "Notably, associations have been reported between schizophrenia and Alzheimer’s disease of polymorphism on the MMP3 promoter, which seems to regulate the transcriptional activity, raising a possibility that the alternation of MMP3 expression may be involved in the etiology of these diseases." (PMID 26633355, 2015). "Another study showed that MMP-3 may be involved in the early pathogenesis of Alzheimer's disease, which may lead to neuronal degeneration, neurofibrillary tangles, and cognitive dysfunction." (PMID 35069415, 2021). "Several SASP factors, including IL-6, IL-1β, TNF-α, MMP-1, MMP-3, and MMP-10, have also been found to be elevated in the cerebrospinal fluid and serum of patients with Alzheimer’s disease." (PMID 37569663, 2023). "CSF concentrations of MMP-9 decrease, concentrations of MMP-3 increase, whilst neither MMP-2 nor TIMPs show significant changes in Alzheimer’s disease patients." (PMID 36232390, 2022).
Hypertension (17 papers, 2013 to 2025). The presence of chronic increased pressure in the systemic arterial system. "Overall, MMP-3 gene variant seems to contribute to the development of hypertension by affecting arterial stiffness." (PMID 34625635, 2021). "Previous genetic epidemiologic study also found the interactions between MMP3 gene polymorphism rs679620 and BMI in predicting blood pressure in African-American women with hypertension." (PMID 24015270, 2013). "MMP-2 and MMP-3 are considered as enzymes initiating hypertension-related remodeling of arteries and large arteries walls stiffening." (PMID 36835040, 2023). "A previous study showed an elevated MMP‐3 level in patients with arterial hypertension." (PMID 33381894, 2021). "A correlation between MMP-3 activity and CIMT was found in untreated subjects with arterial hypertension." (PMID 35011813, 2021).
osteosarcoma (17 papers, 2014 to 2025). A usually aggressive malignant bone-forming mesenchymal neoplasm, predominantly affecting adolescents and young adults. "The analysis of immunohistochemistry data and databases associated a positive correlation between CCL2 or MMP-3 levels with the metastasis of osteosarcoma patients." (PMID 37893141, 2023). "High CTGF expression was significantly associated with clinical stage and metastasis; higher CTGF and lower miR-519d expression were linked with MMP-2 and MMP-3 expression, correlating with osteosarcoma development and metastasis." (PMID 25003330, 2014). "Both CCL2 and MMP-3 were highly expressed in lung metastatic osteosarcoma tissues compared to normal lung tissues." (PMID 37893141, 2023). "In this study, we observed higher levels of CCL2 and MMP-3 expression in lung metastatic osteosarcoma tissues compared to normal lung tissues." (PMID 37893141, 2023). "The expression level of MMP-3 in osteosarcoma patients was significantly higher than in the normal group." (PMID 37893141, 2023). "MMP-3 is more highly expressed in metastatic osteosarcoma than in primary osteosarcoma tumor tissues." (PMID 37893141, 2023). "It has been found that MMP-3 is more highly expressed in metastatic osteosarcoma than in primary osteosarcoma tumor tissues." (PMID 37893141, 2023). "Our clinical sample results showed significantly higher MMP-3 protein and mRNA expression in osteosarcoma patients than in normal individuals." (PMID 37893141, 2023). "To confirm MMP-3’s involvement in osteosarcoma cell migration and invasion driven by CCL2, we treated osteosarcoma cells with an MMP-3 inhibitor or siRNA, both of which resulted in the inhibition of CCL2-induced enhancement of cell migration and invasion." (PMID 37893141, 2023). "Our results revealed a robust increase in MMP3 mRNA expression after CCL2 stimulation in osteosarcoma cells compared to others." (PMID 37893141, 2023). "MMP3 expression levels in stage 3/4 and metastatic osteosarcoma samples are higher than those in stage 1/2 and primary osteosarcoma samples, respectively." (PMID 37893141, 2023). "In conclusion, our findings have revealed that CCL2 downregulates the expression of miR-3659, consequently increasing the expression of MMP-3, thereby promoting osteosarcoma cell motility." (PMID 37893141, 2023). "For example, the increased expression of MMP-3 induces tumor metastasis in osteosarcoma by inhibiting miR-519d, and miR-134 reduces osteosarcoma cell invasion and metastasis by targeting MMP-3 in vivo and in vitro." (PMID 37893141, 2023). "Next, we further examined the expression levels of CCL2 and MMP-3 in metastatic osteosarcoma tissues in vivo from our previous study." (PMID 37893141, 2023). "More recently a study used single cell RNAseq to investigate the cellular heterogeneity within human osteosarcoma specimens and identified MMP-3 as one of the top differentially expressed genes in OSA specimens." (PMID 34414229, 2021). "Researchers compared MMP-3 mRNA levels between tumor cells and osteoblast cells in patients with osteosarcoma and concluded that osteosarcoma tumor cells express more MMP-3." (PMID 34276395, 2021). "On top of that, DK1 was also capable to regulate pro-metastatic genes in both U-2 OS and MG-63 osteosarcoma cell lines; for instance, MMP3, COL1A1, and FGF expression were significantly down-regulated in U-2 OS." (PMID 34204873, 2021). "Subsequent knockout experiments showed that MMP-3 knockout can reduce the migration of tumor cells, which confirmed that MMP-3 contributes to osteosarcoma invasion." (PMID 34276395, 2021). "Further, their data identified miR-519d down-regulation via connective tissue growth factor (CTGF) signaling as a pathway osteosarcoma cells utilize to upregulate MMP-3 and MMP-2 expression." (PMID 27562075, 2016).